CD4 (CD4 molecule)
Diseases named in the same sentence as CD4 in open-access papers (continued):
Sharing a sentence is not in itself a finding about the gene and the disease.
HIV-1 infection (continued). "Altogether, these data suggest that HIV-1 infection may have triggered a pro-survival, OX40-linked pathway in gut CD4+ T cells." (PMID 28241075, 2017). "Thus, major efforts have been made to understand the molecular events that occur following HIV-1 infection of CD4+ T cells." (PMID 28241075, 2017). "However, CD4+ T cells are major targets of HIV-1 infection and provision of cytokines such as interleukin-15 and type I interferons can be used to overcome the requirement of CD4+ T cell help for priming and survival of CD8+ T cells." (PMID 29118747, 2017). "On these grounds, growing evidence suggests that induction of cytotoxic CD4+ T cell responses might be relevant for the successful control of HIV-1 infection and for the development of highly efficient anti-HIV-1 vaccines." (PMID 28289418, 2017). "We also showed that during HIV-1 infection, the high frequency of circulating CD4+CD70+ T lymphocytes in HIV-1-infected individuals was associated with increased plasma IgG levels, upregulation of the B cell activation marker CD38 on memory B cells, and proliferation of memory B cells." (PMID 28473831, 2017). "Another important progressive effect on lymph node architecture during chronic HIV-1 infection is increasing deposition of collagen in T cell areas, which may severely and irreversibly disrupt CD4 T cell homeostasis." (PMID 28553284, 2017). "However, these cells are less permissive to HIV-1 infection compared to activated CD4+ T-cells, mainly due to host restriction factors that control the establishment or spread of viral infection." (PMID 29176984, 2017). "The altered CD4+ memory and regulatory cells occur during HIV-1 infection are recovered by ART." (PMID 28279181, 2017). "We then tested whether the disruption of CXCR4 and CCR5 on primary CD4+ T cells protected cells from HIV-1 infection." (PMID 28904745, 2017). "Human immunodeficiency virus type-1 (HIV-1) infection of monocyte/macrophages is modulated by the levels of entry receptors cluster of differentiation 4 (CD4) and C-C chemokine receptor type 5 (CCR5), as well as by host antiviral restriction factors, which mediate several post-entry blocks." (PMID 29301198, 2017). "Indeed, there were early signs that, in the acute HIV-1 infection, up to 60% of all activated memory CD4+ T cells are infected and subsequently depleted from all tissue compartments." (PMID 28289418, 2017). "Human primary CD4+ T cells are the major target for HIV-1 infection." (PMID 28904745, 2017). "In the control group, the let-7i mimic still significantly decreased the HIV-1 infection-induced apoptosis of CD4+ T cells, but when IL-2 was knocked down, the apoptosis caused by HIV-1 infection was not rescued by let-7i overexpression." (PMID 27145859, 2016). "However, we report here consistent m6A mapping results using Jurkat T-cells and primary CD4+ T-cells and systematic evaluation of the roles of the m6A writers, readers, and erasers in HIV-1 infection." (PMID 27371828, 2016). "Collectively, these findings demonstrate a novel approach to enhance the fusion-inhibiting properties of HR2 peptides and to confer broad and durable protection from HIV-1 infection to CD4 T cells by directly targeting the peptides to the precise site of fusion and viral entry." (PMID 27855210, 2016). "However, the activation status of T cells with productive HIV-1 infection (i.e. CD4+ and DN T cells), or CD8 T cells at sites of HIV/TB co-infection have not been characterized." (PMID 27870882, 2016). "We studied if an even higher increase in T-cell loss and division rates during the early stage of infection could explain the observed biphasic decline of the average TREC content and the decline in naive CD4+ T-cell counts in HIV-1 infection." (PMID 27010200, 2016).
HIV-1 infection (continued). "In conclusion, we found that HIV-1 infection impairs Mtb-specific responses not only by numerically reducing Mtb-specific CD4+ T cells but also alters the balance of their functional profile, and show for the first time the selective depletion of IFN-γ single positive cells." (PMID 27865393, 2016). "One may speculate that in chronic HIV-1 infection, CD4 and CD8+ T cells that are poorly responsive to normal physiological and homeostatic pathways involving IL-15, may need higher circulating levels of IL-15 to remain functional." (PMID 27880829, 2016). "Nearly all HAMB species increased HIV-1-associated CD4 T cell depletion relative to HIV-1 infection without HAMB." (PMID 26762145, 2016). "Furthermore, knockdown of individual, endogenous YTHDF1–3 proteins in activated primary CD4+ T-cells from healthy donors enhanced HIV-1 infection by approximately two-fold (p<0.005), confirming the effects observed in cell lines despite a lesser extent." (PMID 27371828, 2016). "To determine if any of the 12 known cytosolic SULTs might play a role in regulating HIV-1 infection, we first compared their relative expression levels in the two physiologically relevant cell types, primary human CD4+ T cells and primary monocytic cells." (PMID 26906565, 2016). "Accordingly, we hypothesized that HIV-1 infection could reduce the IL-2 expression by downregulating let-7i miRNA, leading to the death of both infected and bystander activated CD4+ T cells." (PMID 27145859, 2016). "The sequence of events which we found to induce production of infectious virions from uDNA mimics an in vivo situation where an infected resting CD4 T cell is activated following migration to lymphoid tissues, which has been proposed as a mechanism facilitating the establishment of HIV-1 infection." (PMID 26728316, 2016). "HIV-1 infection leads to depletion of SAMHD1- cells in activated CD4+ T cells." (PMID 27922067, 2016). "Increased binding of HIV-1 particle through MMR or DC-SIGN might enhance transmission of infection to CD4+ T cells, however this effect might be limited in the case of HIV controllers due to the relative resistance of their CD4+ T cells to HIV-1 infection." (PMID 27505169, 2016). "Additionally, we selected for cells with relatively high CD4 levels, which is typically useful for studying HIV-1 infection (right panel red bars)." (PMID 26969387, 2016). "In addition, it is well known that the main target of HIV-1 infection is human CD4+ T cells and monocytes/macrophages." (PMID 27086687, 2016). "We first confirmed the effects of IL-2 in maintaining CD4+ T cell survival in HIV-1 infection." (PMID 27145859, 2016). "Multiple studies have attempted to explain the depletion of CD4 T cells during HIV-1 infection." (PMID 27026376, 2016). "However, efforts aimed at stimulating such approaches to develop a vaccine against HIV-1 have been so far unsuccessful, possibly because most vaccine prototypes were aimed at rapidly activating CD4+ T-cells after HIV-1 infection." (PMID 27148256, 2016). "Thus, endogenous YTHDF1–3 proteins in CD4+ T-cells act as negative regulators to inhibit post-entry HIV-1 infection." (PMID 27371828, 2016). "Pre-existing elevated IP-10 levels but not sCD63 associated with rapid CD4 T-cell loss upon HIV-1 infection." (PMID 27509048, 2016). "Here, we investigated whether these changes in T-cell dynamics suffice to explain the observed biphasic loss of TRECs in naive T cells concomitant with a continual loss of naive CD4+ T cells and stable naive CD8+ T-cell numbers during HIV-1 infection." (PMID 27010200, 2016). "It was recently proposed that pyroptosis, a form of cell death, could lead to depletion of CD4+ T cells during HIV-1 infection." (PMID 27596745, 2016). "The contribution of immune activation at sites of HIV/TB co-infection to viral activity, CD4 T cell count, and productive HIV-1 infection remain unclear." (PMID 27870882, 2016).
HIV-1 infection (continued). "It has been hypothesized that HIV-1 infection, pathogenesis of which leads to a decreased level of CD4+ cell counts may affect the development of hepatic morbidities in HIV-1/S." (PMID 25948238, 2015). "We are currently investigating the function of CD4+CD8+ T cells in relation to HIV-1 infection." (PMID 26034905, 2015). "Intestinal CD4+ T cell depletion is rapid and profound during early HIV-1 infection." (PMID 26696749, 2015). "Notably, we found that lower HIV-1 infection in IL-21-treated HLACs resulted in improved CD4/CD8 T-cell ratio (less CD4 depletion) in these cultures." (PMID 26108174, 2015). "First, CD4:CD8 ratio was rarely measured before acquisition of HIV-1 infection." (PMID 26191056, 2015). "Indeed, extreme permissiveness of Th17 cells to HIV-1 infection can be explained based on the fact that mucosal CD4+ T cells present a CD45RO+ memory phenotype and express CCR5 and/or CXCR4." (PMID 26568963, 2015). "Latently infected CD4+ cells are produced with a fraction μ during HIV-1 infection." (PMID 26709961, 2015). "However, the ability of Nef to selectively eliminate CD4 from exosomes suggests yet another mechanism by which Nef promotes HIV-1 infection." (PMID 26205405, 2015). "Interestingly, IL-1β and IL-6 enhance HIV-1 infection in monocytes and resting CD4+ T cells in vitro." (PMID 25785697, 2015). "Certain characteristics seen in subjects with a favorable CD4:CD8 ratio, including HLA variants, may offer valuable insights into the determinants or mechanisms of immunologic health in HIV-1 infection." (PMID 26191056, 2015). "How HIV-1 infection induces progressive CD4+ T cell depletion is unclear." (PMID 26709961, 2015). "HIV-1 infection is characterized by a gradual decrease of the immunological competence and a massive depletion of CD4+ T cells, particularly in GALT, which leads to microbial translocation, contributing to immune hyperactivation, an important pathogenic mechanism HIV-1 infection." (PMID 26568963, 2015). "Second, although active IDU in the absence of HIV-1 infection does not result in depletion of CD4+ T lymphocytes per se, it is associated with activation of the immune system." (PMID 26925299, 2015). "Human CD4+ T cells are the major target cells of HIV-1 infection." (PMID 26481100, 2015). "HLACs provide more physiologically relevant HIV-1 infection conditions since, unlike peripheral blood CD4 T cells lymphoid CD4 T cells are susceptible to HIV-1 infection without mitogenic stimulation." (PMID 26108174, 2015). "In addition, HIV-1 infection of macrophages has been shown to modulate apoptosis and promote infection of resting CD4+ T cells." (PMID 25835530, 2015). "Numerous studies indicate that the initial targets of HIV-1 infection could primarily be CD4+ T cells, with dendritic cells (DC), Langerhans cells (LC), and/or macrophages also playing a role." (PMID 26052926, 2015). "HIV-1 infection is associated with functional impairment of HIV-1-specific CD8+ and CD4+ T cells." (PMID 26713320, 2015). "The primary cell targets of HIV-1 infections (discussed in detail in section 3.6) include the CD4+ T lymphocytes and monocyte/macrophage lineages, while other cells were found to be capable of getting infected with HIV-1 including natural killer, CD8+, B and follicular dendritic cells." (PMID 29061947, 2015). "Therefore, high levels of IFNγ stimulate the clonal expansion of CD4+ T lymphocytes to promote the maintenance of a response during the course of HIV-1 infection." (PMID 25802474, 2015). "In this study, we have provided sufficient evidence that functional state of myeloid dendritic cells is more severely affected during advanced stage of HIV-1 infection when the CD4+ T-cell counts fall below 250 cells/μL, making these patients more prone to opportunistic infections." (PMID 26492336, 2015).
HIV-1 infection (continued). "Differences in immune parameters have been found according either to different immunological response to ART (reflected by the magnitude of CD4+ T-cells recovery), or to different degree of immunedeficiency at presentation or during the course of HIV-1 infection (reflected by CD4+ T-cells nadir)." (PMID 25671649, 2015). "Initial studies in vitro, showed that direct HIV-1 infection of resting CD4+ T-cells isolated from peripheral blood was inefficient and integration rarely occurred due to incomplete reverse transcription, reduced nuclear import of the viral DNA and/or limited integration within the host genome." (PMID 26362311, 2015). "It is interesting that, as previously reported, the frequency of PD-1+ memory CD4+CD45RO+T cells was increased during HIV-1 infection in viremic children, suggesting a specific damage to take place in PD-1 expressing memory Tfh cells which are reduced in frequency." (PMID 26166114, 2015). "However, despite the success of cART, a latent form of HIV-1 infection persists as integrated provirus in resting memory CD4+ T cells." (PMID 26441979, 2015). "Concurrent lower level CD40 expression on antigen presenting cells may contribute to an impaired CD4 T cell response to antigen in vivo; a recognized complication of HIV-1 infection." (PMID 26430882, 2015). "Increased expression of CD38 and HLA-DR on CD4+ and CD8+ T cells in untreated HIV-1 infection has been associated with rapid disease progression and that degree of immune reconstitution following combination antiretroviral therapy is inversely associated with immunological activation." (PMID 26925299, 2015). "CD4+ T cells from older individuals were highly susceptible to CXCR4- and CCR5-tropic HIV-1 infection but produced significantly lower quantities of infectious virus than cells from young individuals because they were highly prone to apoptosis and thus presumably had a very short life span." (PMID 26452480, 2015). "We and others have shown that cocaine also promotes HIV-1 infection/replication in CD4+ T cells." (PMID 26539167, 2015). "Moreover, it has been shown that disruption of CCR5 receptor of autologous CD4+ T cells by zinc finger nucleases (ZFNs) can efficiently inhibit HIV-1 infection in CD4+ T cells." (PMID 26481100, 2015). "Non-progressive HIV-1 infection was associated with small but significant increases in Ki-67 expression in both the CD4+ and CD8+ T-cell populations, while SIVcpz appeared to induce a similar or smaller (and not significant) effect." (PMID 26360709, 2015). "Mononuclear cells were recovered at sacrifice (day 14 after HIV-1 infection) from the peritoneal cavity and spleen, and CD4+ T cells were markedly reduced relative to CD8+ T in the control mice, while the ratio was relatively preserved in mice transplanted with shPromA-transduced cells." (PMID 25625613, 2015). "Indeed, CD4-loaded exosomes efficiently inhibit HIV-1 infection, while CD4-depleted exosomes isolated from CD4+ T cells expressing Nef have a reduced capacity to inhibit HIV-1 infection." (PMID 26205405, 2015). "We have found that apoptotic microparticles, which reach high concentrations in the circulation during acute HIV-1 infection as extensive destruction of CD4 T cells occurs, inhibit DC functions, impairing the ability of DCs to produce IL-12 and prime T cell responses." (PMID 25569444, 2015). "Indeed, NKT cell frequency is reduced in patients with HIV-1 infection, with a preferential depletion of the CD4+ NKT cell subset prior to depletion of conventional CD4+ T cells." (PMID 26074921, 2015). "Thus, the replacement of all or part of the immune system through genetic engineering to produce CD4+ T cells resistant to HIV-1 infection is a more feasible strategy." (PMID 26588898, 2015). "SAMHD1 restricts HIV-1 infection of myeloid-lineage and resting CD4+ T-cells." (PMID 26431200, 2015).
HIV-1 infection (continued). "Importantly, the ability of IL-21 to overcome HIV-1-induced miR-29 downregulation was consistent with its ability to also suppress HIV-1 infection when added to HLACs after CD4 T cells have been infected with HIV-1." (PMID 26108174, 2015). "Interestingly, we found that HIV-1 infection (as measured by GFP+CD3+) of CD4 T cells in IL-21-treated HLACs was significantly reduced compared with untreated cultures." (PMID 26108174, 2015). "It has been hypothesized that the destructions of CD4+ T-lymphocytes by HIV-1 infection may alter the sizes of the left liver lobe and the patterns of hepatic fibrosis." (PMID 25948238, 2015). "HIV-1 infection remains incurable due to the latently infected CD4+ T cells." (PMID 26643614, 2015). "During the late course of HIV-1 infection where CD4+ T cells are largely depleted, CNS resident HIV-1-infected cells might represent the source of viral persistence in the infected individuals." (PMID 26405463, 2015). "Interestingly, we found that humanized mice treated with exogenous IL-21 were largely protected from early HIV-1 infection and reduced viral load in these animals correlated with higher miR-29 expression in splenic CD4 T cells." (PMID 26108174, 2015). "In particular, the RV144 trial demonstrated that CD4+ T cell-mediated responses, but not CD8+ T cell-mediated responses, were predominantly effectively elicited in vaccinees, and the CD4+ T cell response correlates and contributes to protection efficacy against HIV-1 infection." (PMID 24671203, 2014). "Ex vivo modeling studies of HIV-1 infection of primary human CD4+ T cells indicated that HIV-1-mediated killing could occur in both productively-infected and bystander, or nonproductively-infected, cells." (PMID 24495380, 2014). "CD4+ T cells are principal targets for human immunodeficiency virus type 1 (HIV-1) infection." (PMID 24517971, 2014). "However, in some patients with HIV-1 infection, a substantial proportion (10-30%) of individuals show incomplete or poor CD4 cell recovery on HAART despite suppression of HIV-1 to undetectable levels." (PMID 24938526, 2014). "We then assessed the relationship between productive HIV-1 infection and LP CD4+ T cell depletion." (PMID 24495380, 2014). "More research is needed to address if extracellular vesicles originated by distinct CD4 T cells subsets convey differential immune functions, and how their cross talk contributes for the regulation of the immune response and for the outcome of HIV-1 infection." (PMID 25295039, 2014). "The pathogenesis of CD4 T cell decline during chronic HIV-1 infection is slow and complex." (PMID 25610441, 2014). "In this study we examine the consequences of HIV-1 infection to naïve and memory resting CD4+ T cells, finding that CD62L was specifically down-modulated, the early activation marker CD69 was upregulated, and that these occurred concomitantly with HIV-1 suppression of Foxo1 activity." (PMID 25330112, 2014). "Chronic HIV-1 infection of NOD/scid-IL-2Rgcnull mice transplanted with human CD34+ hematopoietic stem cells (CD34-NSG) leads to persistent viremia, profound CD4+ T lymphocyte loss and infection of human monocyte-macrophages in the meninges and perivascular spaces." (PMID 25523827, 2014). "Because CCR5, CXCR4 and CD4 expression or differences in cell growth could affect HIV-1 infection, we compared CXCR4 and CD4 expression and cell growth of CCR5-/CR1, CCR5-/CR2 and CCR5-/CR3 cells with those of mock-transduced TZM.bl cells." (PMID 25541967, 2014). "HIV-1 infection ultimately results in the depletion of CD4+ T and CD8+ T cells." (PMID 26056579, 2014). "Presented another way, 63% of the CD4+ T cells committed to dying (AnnexinV+) were p24neg and had a necrotic phenotype, indicating that necrotic cell death in the p24neg population accounted for the majority of depletion during HIV-1 infection." (PMID 24495380, 2014).